CD5 (CD5 molecule)
Diseases named in the same sentence as CD5 in open-access papers (continued):
Sharing a sentence is not in itself a finding about the gene and the disease.
infectious disease (6 papers, 2016 to 2024). A disorder directly resulting from the presence and activity of a microbial, viral, or parasitic agent in humans. "Although the application of the organoid model has greatly affected the area of infectious disease research, the CD5 index shows that its disruptiveness is relatively neutral." (PMID 38926765, 2024). "Markers such as CD5 have allowed the differentiation of B-1 cell subsets, with perhaps the most studied and consistent change during infectious disease being a shift to CD5+ B cells, defined as the B-1a B cell subset." (PMID 36477266, 2022). "The reasons for the apparent different behaviors of CD5+ and CD5- B-1 cells in the various infectious disease models are unexplained." (PMID 31433296, 2019). "Although no known function for these CD5+ subpopulations has been elucidated yet, the reproducibility in more than one cattle study suggests potential functional differences during infectious disease." (PMID 36477266, 2022). "Therefore inflammatory-disease specific eQTLs, such as the eQTL for CD5 and CD6, may be important for understanding the heterogeneity of clinical course in autoimmune and infectious diseases." (PMID 27015630, 2016).
bacterial infections (4 papers, 2007 to 2024). "B1b cells (CD19+CD43+CD5-) are important in providing protection against acute bacterial infections and producing vaccine responses." (PMID 38111533, 2023). "By means of CD5- and CD6-deficient mice, it has been demonstrated that both lymphocyte receptors are integral and non-redundant components of the host’s immune defence against fungal and bacterial infections." (PMID 39452619, 2024). "Studies in CD5 and CD6 knockout mice showed relevant and non-redundant roles in immune defence toward fungal and bacterial infection, respectively." (PMID 39452619, 2024).
inflammation (2 papers, 2016 to 2022). Aberrant reaction of the microcirculation characterized by movement of fluid and leukocytes from the blood into extravascular tissues. "Because pTreg deficiency can cause gut inflammation, we speculated that CD5 KD may promote gut immune dysfunction by inhibiting pTreg formation." (PMID 35720357, 2022).
neurological disease (2 papers, 2025). "In the drug feasibility evaluation, by investigating potential drug development targets for CD5, which exhibits robust associations with CP, a promising candidate for neurological disorder drug development, protein CXCR4, was identified." (PMID 40988181, 2025). "Ten proteins showed co-localization with a neurological disease using both plasma protein abundance and plasma mRNA abundance (SIRPA, CTSH and CD33 with AD; and ASF1A, FCRL3, VEGFB, TYMP, PVALB, LMAN2 and CD5 with MS)." (PMID 40037332, 2025).
heart disease (1 paper, 2023). "For example, CD5-targeted mRNA-LNPs were used to generate CAR-T cells in vivo in a mouse model of heart disease." (PMID 37805495, 2023).
hematopoietic neoplasm (1 paper, 2025). "Three main subsets were identified in healthy cats and diseased cats without hematopoietic neoplasm (namely, CD5 + CD45R-, CD21 + CD45R + and CD5 + CD45R+)." (PMID 40822655, 2025).
CD5 also shares sentences with these, for which no sentence is quoted: Allergy (3 papers); Graves disease (3); neutropenia (3); vasculitis (3); ANCA-associated vasculitis (2); Chronic Myelogenous Leukemia (2); CNS DLBCL (2); colon cancer (2); esophageal cancer (2); glioma (2); Hepatic fibrosis (2); leukocytosis (2); osteosarcoma (2); Salmonella Infections (2); T cell chronic lymphocytic leukemia (2); thymic epithelial neoplasm (2); ulcerative colitis (2); undifferentiated carcinoma (2); undifferentiated thyroid carcinoma (2); Waldenström's macroglobulinemia (2); adenocarcinoma (1); alcoholic liver cirrhosis (1); alcoholism (1); Alzheimer disease (1); angioimmunoblastic T-cell lymphoma (1); Atopic Dermatitis (1); autoimmune encephalitis (1); B-cell lymphopenia (1); Behçet's disease (1); cerebral amyloid angiopathy (1).
A further 70 diseases each share a sentence with CD5 in 1 paper.